APLN (apelin)
Diseases named in the same sentence as APLN in open-access papers (continued):
Sharing a sentence is not in itself a finding about the gene and the disease.
tumor (continued). "In cancer development, apelin is implicated in activating the apelin receptor, APJ, which is overexpressed in tumor tissues." (PMID 38255203, 2024). "Several correlation studies have recently indicated that apelin plays a role in tumor progression, with advanced stages of BCa showing high apelin expressions." (PMID 39040042, 2024). "The elevation of MVD and AVD in tumour tissue is likely due to the overexpression of APJ in tumour‐associated vasculature and the activation of the APJ signalling pathway by Apelin." (PMID 39434201, 2024). "KEGG pathway analysis revealed that the genes associated with the upregulated eccDNAs in group B are involved in sphingolipid signaling, apelin signing, and tumor-related signaling pathways, such as the MAPK and WNT signaling pathways." (PMID 38903532, 2024). "In gastroesophageal cancer, patients’ APLN levels were significantly higher in tumor tissue and serum than in healthy controls." (PMID 36614283, 2023). "Growing evidence has suggested that apelin induces the maturation of tumor blood capillaries and stimulates the proliferation of smooth muscle cells by modifying cyclin D1 expression and favoring the progression of cell cycle." (PMID 36902176, 2023). "In subcutaneous inoculation of tumor cell mouse models, we previously reported that overexpression of apelin in colon 26 tumor cells significantly inhibited tumor growth by promoting penetration of natural killer T cells into the tumor." (PMID 36776217, 2023). "The function of APLN in tumor development and metastasis can be elucidated by the regulation of mediators controlled in tumor initiation and metastasis." (PMID 36632453, 2023). "For example, Colon 26 tumors showing apelin overexpression in mice after subcutaneous implantation inhibited tumor growth." (PMID 36776217, 2023). "In this report, to clarify the effect of apelin in tumor cells, we analyzed the function of APJ in tumor cells using APJ knock out (KO) mice." (PMID 36776217, 2023). "Based on our present studies, we showed that apelin has a role in tumor progression, affecting tumor cells directly." (PMID 36776217, 2023). "APLN/APLNR signaling has been demonstrated to associate with neovascularization, tumor vessel density, microvascular proliferation, and tumor growth in other types of tumors." (PMID 36959862, 2023). "Studies have shown that inhibition of the APLN–APLNR axis by a pharmacological targeting against APLN can reduce tumor growth." (PMID 36614283, 2023). "When LuCaP96 castrated and non-castrated samples were compared, 19/41 genes in CTCs and 5/41 genes in primary tumours were significantly different, with genes APLN and CD44 being significantly different in both comparisons." (PMID 35493092, 2022). "In human tumor cells, apelin induced a long-lasting activation of PI3K/Akt, upregulated β-catenin and the oncogenes c-myc and cyclin D1 and promoted proliferation, migration and glucose uptake." (PMID 36142542, 2022). "Silencing the apelin Signaling pathway either by knocking down or blocking the APLNR reduces tumor volume, vascularization, and proliferation." (PMID 36421846, 2022). "In pan-tumor tissues, APLN was significantly increased in 15 datasets, while 3 datasets showed a decreased level." (PMID 36193059, 2022). "In non-small-cell lung cancer (NSCLC), APLN mRNA was significantly upregulated in tumor tissue compared with normal lung, and high level of APLN protein was reported to be associated with the increased microvessel densities and worse overall survival." (PMID 36193059, 2022). "Among them, leptin, resistin, visfatin and apelin are abundant in the plasma of obese individuals, correlate positively with the amount of fat, and have tumor-promoting functions." (PMID 36291097, 2022). "Apelin, found most often in the heart, lungs, and mammary glands, plays a role in many physiological processes such as apoptosis, inflammation, and tumor proliferation." (PMID 36230579, 2022).
tumor (continued). "These treatments have been shown to decrease the apelin expression inside the tumor, thus, increasing its invasiveness." (PMID 36421846, 2022). "The dysfunction of apelin, a cytokine secreted from adipose tissue, plays a role in tumor metastasis by enhancing cell proliferation, migration and cell survival." (PMID 36291151, 2022). "Apelin blockade significantly suppressed tumor growth, according to IVIS imaging and manual tumor weight measurements." (PMID 36291151, 2022). "Previous research reported that tissue apelin concentration correlated with tumor growth and metastasis suggesting the vascular effects of apelin." (PMID 36230579, 2022). "Studies have shown that high expression of apelin can promote tumor angiogenesis in malignant tumors such as lung and liver cancers." (PMID 34778094, 2021). "In these tumor models, APLN expression levels directly correlated with the rate of angiogenesis and survival." (PMID 34359800, 2021). "To clarify how EC-secreted Apelin inhibits tumor growth in the MC38 model, first, we evaluated tumor vessel formation." (PMID 34234274, 2021). "The role of tumor-cell derived APLN was investigated by shRNA-mediated APLN knock-down (APLN-KD), which demonstrated that depletion of APLN expression from tumor cells also decreased tumor vessel density (independently from host-derived APLN)." (PMID 34359800, 2021). "In the present study, we suggest that Apelin’s ability to inhibit tumor growth depends on the particular tumor model studied." (PMID 34234274, 2021). "In summary, recent research on APLN/APLNR signaling in tumor pathology indicates that pharmacological modulation of the APLN/APLNR pathway can act as anti-angiogenic and anti-invasive treatment." (PMID 34359800, 2021). "These experiments highlighted intratumoral ECs as one major source for APLN in neoplasia and suggested that autocrine APLN/APLNR signaling in ECs co-controls tumor angiogenesis." (PMID 34359800, 2021). "Compared with the saline control (WT + Saline), the MC38 tumor exhibited decreased growth in mice infused with Apelin (WT + [Pyr1]Apelin-13)." (PMID 34234274, 2021). "Collectively, therefore, these data imply that Apelin regulates tumor growth through an Apelin/APJ autocrine pathway in ECs or in a paracrine manner between neighbouring ECs." (PMID 34234274, 2021). "In our previous study, overexpression of Apelin significantly inhibited colon 26 tumor growth in mouse subcutaneous inoculation models." (PMID 34234274, 2021). "In a metastatic mice model, where the tumor cells were injected intravenously, we found that apelin overexpression significantly increased both the number and size of lung metastases." (PMID 33707612, 2021). "Experimentally reducing APLN expression in orthotopic (syngeneic or xenograft) models for GBM led to increased tumor invasiveness." (PMID 34359800, 2021). "In muscle-invasive bladder cancer, apelin protein expression level was elevated in tumor tissues compared with adjacent normal tissues." (PMID 33912466, 2021). "Here, we found that MC38 and LLC tumor growth were greater in the absence of Apelin than in wild-type (WT) mice, suggesting that Apelin acts as a tumor suppressor." (PMID 34234274, 2021). "In any event, these differences in different tumor models indicate that Apelin has diverse functions in tumor formation depending on the intratumoral conditions." (PMID 34234274, 2021). "In that paper, the authors showed that APLNR-positive tumor cells started to disseminate when Apelin levels were reduced both in in vitro and in vivo, and that data from patient samples were consistent with this in humans." (PMID 34234274, 2021). "This was confirmed by qRT-PCR and indicates that ECs are the major source of Apelin affecting tumor growth in this model." (PMID 34234274, 2021). "Investigating immune cells in the tumor revealed that [Pyr1]Apelin-13 infusion induced the accumulation of CD8+ and CD4+ T cells in central areas." (PMID 34234274, 2021).
tumor (continued). "In BC and lung cancers, the combined inhibition of apelin and angiogenesis (i.e., sunitinib) powerfully reduces tumor growth and angiogenesis rates." (PMID 33670492, 2021). "Using this model, we determined how Apelin affects tumor vascularity, focusing on structure and function, and in particular, immune cell infiltration." (PMID 34234274, 2021). "In contrast, high APLN expression levels were restricted to tumor cell-dense and highly vascularized areas of the main tumor mass." (PMID 34359800, 2021). "For instance, apelin was reported to induce enlargement of blood vessels in the dermis of apelin Tg mice, and overexpression of Apelin in colon 26 tumor cells significantly suppressed tumor growth by inducing tumor vascular maturation." (PMID 34234274, 2021). "Taken together, these results indicate that apelin-mediated elongation and enlargement of tumor vessels also induces their functional maturation in the MC38 model." (PMID 34234274, 2021). "Since then, several studies demonstrated that apelin is a potent activator of tumor neoangiogenesis." (PMID 33707612, 2021). "Corresponding to Apelin function in normal tissues, WT mice exhibited longer tumor blood vessels relative to their Apelin-KO tumor-bearing counterparts." (PMID 34234274, 2021). "The overexpression of apelin not only stimulated tumor growth but also led to increased intratumoral lymphangiogenesis." (PMID 34068679, 2021). "It remains to be shown if Apelin and its receptor also control tightness of the blood tumor barrier in GBM." (PMID 34359800, 2021). "Apelin is significantly induced in various tumors and has a role in cell proliferation (especially on CSCs), tumor development and metastasis (by stimulating angiogenesis), and drug resistance." (PMID 33670492, 2021). "The MC38 colon cancer cell subcutaneous inoculation model was found suitable for analysing the tumor suppressive function of Apelin." (PMID 34234274, 2021). "Apelin is upregulated in NSCLC compared to healthy lung tissue and is associated with tumor growth and progression." (PMID 33670492, 2021). "In order to clarify the effect of exogenous Apelin, further analysis of the mechanism by which Apelin induces enlargement of vascular structures in the tumor microenvironment is required." (PMID 34234274, 2021). "APLNR and its ligand apelin are involved in promoting tumor angiogenesis via multiple autocrine and paracrine mechanisms." (PMID 35052372, 2021). "Together with a comparative study of gene expression profiles in tumor versus normal endothelium, this was the first indication for an angiogenic role of APLN in human tumors." (PMID 34359800, 2021). "In a previous publication, it has been reported that Apelin overexpression combined with αGalCer/DCs treatment improves iNKT cell infiltration, which leads to a tumor-inhibitory effect." (PMID 34234274, 2021). "To study if tumor cell-derived APLN controls angiogenesis-dependent GBM growth, we first tested widely used GBM cell lines for APLN expression, revealing differing levels of expression." (PMID 32545380, 2020). "The APJ receptor antagonist F13A was used to block apelin/APJ signaling to inhibit tumor growth and small arteries in an HCC subcutaneous murine tumor model." (PMID 33171641, 2020). "By in situ hybridization on GBM patient specimens, we found the first indication of a role for apelin signaling in tumor development." (PMID 32545380, 2020). "Ex vivo analysis of infused tumours revealed that apelin infusion significantly increased tumour apelin mRNA expression." (PMID 32681609, 2020). "A correlation between high circulating apelin and tumour grade or overall bad prognosis has previously been described." (PMID 32681609, 2020). "To investigate the potential role played by apelin on tumour growth, we combined different models and pharmacological approaches." (PMID 32681609, 2020).
tumor (continued). "To investigate the impact of APLN expression derived from the tumor microenvironment, namely APLN expressed on endothelial tip cells during sprouting angiogenesis, we implanted GL261 cells into APLNKO mice." (PMID 32545380, 2020). "The depletion of both, tumor and host APLN in U87AKDAPLNKO xenografts further reduced VLD by 61% as compared to U87NSCAPLNWT control." (PMID 32545380, 2020). "On the other hand, another study suggested that tumour apelin expression was more accurately correlated with increased tumour progression." (PMID 32681609, 2020). "Apelin expression in tumors is regulated by hypoxia and is suggested to promote tumor growth in several ways." (PMID 31690961, 2020). "Intracerebral implantation of GBM cell lines with different APLN expression levels showed that tumor-derived apelin is required for the formation of the GBM neo-vasculature." (PMID 32545380, 2020). "This experiment demonstrated that apelin is important for tumor angiogenesis and that compact subcutaneous tumors depend on the apelin-induced neo-vasculature for their growth." (PMID 32545380, 2020). "While vessel branching reflects the picture observed by VLD assessment, the total vessel length (that is the VLD multiplied by the individual tumor volume) was highly reduced in all three xenografts with reduction of APLN expression." (PMID 32545380, 2020). "Because of the anti-angiogenic and anti-lymphangiogenic abilities of Apelin, Apelin has been proposed as a potential therapeutic target for tumor therapies." (PMID 33614496, 2020). "By this blockade of APLN-dependent tumor angiogenesis, tumor growth was reduced and survival of GBM-bearing mice was, in turn, increased." (PMID 32545380, 2020). "Reduction of apelin expression in tumor cells attenuated tumor angiogenesis and ectopic infusion of apelin-13 peptide specifically reversed this vascular GBM phenotype." (PMID 32545380, 2020). "We confirmed a causal link between increased apelin expression in obese mice and larger TNBC tumours with two different approaches." (PMID 32681609, 2020). "Next, we wanted to study the contribution of GBM cell-derived APLN to tumor angiogenesis and thus we compared vascular patterns generated by U87MG cells with a stable knock-down for APLN (U87AKD) to non-silencing control cells (U87NSC)." (PMID 32545380, 2020). "Using these infiltrative GBM mouse models, we found increased in vivo, as well as in vitro, invasion, when the tumor cells lost autocrine apelin signaling." (PMID 32545380, 2020). "Apelin-based synNotch receptors (AsNRs) support the implementation of the detection and transformation of apelin/Apj signals, which provides novel evidence for tumor detection." (PMID 32358530, 2020). "The results of our study fit with previous in vivo observations made, where ectopic apelin overexpression enhanced angiogenesis and tumor cell proliferation in subcutaneous tumor models." (PMID 32545380, 2020). "Previously, ectopic expression of APLN in subcutaneous tumors was described to stabilize tumor vessels and support vascular maturation." (PMID 32545380, 2020). "During the past few years, several studies have shown a correlation between tumour growth and plasma levels or tumoral expression levels of apelin." (PMID 32681609, 2020). "Apelin mRNA expression was also increased in the subcutaneous adipose tissue and tumours of obese mice." (PMID 32681609, 2020). "Apelin also stimulates neoangiogenesis and microvascular proliferation within the tumor, leading to enhanced tumor growth." (PMID 31690961, 2020). "Strikingly, if APLN was missing in the tumor microenvironment, the tumor volume decreased to less than 15% compared to WT controls." (PMID 32545380, 2020). "By immunohistochemical staining of human HCC specimens, APLN was located in the cytoplasm of tumor tissues with higher expression as compared to adjacent normal tissues (P < 0.01)." (PMID 31410213, 2019).
tumor (continued). "It would be interesting to compare the expression of APLNR/APLN in paired samples from primary tumours and metastases." (PMID 30783205, 2019). "In tumor cells, APLN gene expression is induced by hypoxia, but its overexpression can be hypoxia-independent when caused by genomic alterations." (PMID 31434359, 2019). "We found that both Apelin sources are of equal importance for the Apelin‐mediated increase in tumor growth." (PMID 31267692, 2019). "The secretion of APLN protein by tumor cells induces AKT phosphorylation and caspase inhibition influencing the growth of CRC." (PMID 31434359, 2019). "We further show that Apelin depletion remodels the tumor microenvironment, by improving vessel leakiness, reducing hypoxia, and decreasing infiltration of PMN‐MDSCs, while increasing NK T cells." (PMID 31267692, 2019). "We found that apelin protein level was upregulated in muscle-invasive bladder cancer and high level expression of apelin was correlated with high tumor stage, distant metastasis, vascular invasion, and poor survival in muscle-invasive bladder cancer patients." (PMID 30984306, 2019). "Next, we examined the functional consequences of combined Apelin inactivation and anti‐angiogenic therapy on local hypoxia and leakage of the tumor vasculature." (PMID 31267692, 2019). "Subsequently, apelin proved to play a vital role in tumor neoangiogenesis through a paracrine effect on the host vessels and its mRNA expression level was increased in 49 tumors." (PMID 30984306, 2019). "Marked reduction in the mRNA expression of apelin and the apelin receptor were evident in hearts of tumor-bearing mice." (PMID 31851697, 2019). "Having established that Apelin is a modulator of tumor blood vessels, we next explored gene expression changes of CD31+/CD105+ endothelial cells (ECs) sorted from Apelin wild‐type and Apln‐depleted tumors." (PMID 31267692, 2019). "Using gene expression & transcriptome analysis, we identified Apelin (APLN) as an outlier gene highly expressed in both NAFLD- and HBV-associated HCC compared to their respective adjacent non-tumor tissues." (PMID 31410213, 2019). "Despite the known role of Apelin in tumor angiogenesis, the detailed effects of Apelin within the tumor cells and its microenvironment in vivo remain poorly understood." (PMID 31267692, 2019). "Patients characterized by high tumor apelin expression had a shorter overall survival period than those with low expression." (PMID 31547096, 2019). "Clinical trials are underway to determine if a reduction in serum apelin levels can be used to assess the efficacy of bevacizumab treatment as a measure of tumor vasculature normalization following similar observations in a mouse model." (PMID 31492821, 2019). "We also observed a link between apelin and its receptor concentration in tumor and non-tumor tissue." (PMID 31547096, 2019). "In line with enhanced survival, Apelin‐null mice displayed a decreased tumor burden in the mammary glands compared to age‐matched controls (Fig EV1D)." (PMID 31267692, 2019). "We show that Apelin inhibition potently remodels the tumor microenvironment, reducing angiogenesis, and effectively blunting tumor growth." (PMID 31267692, 2019). "Pharmacologic inhibition of Apelin signaling by MM54 had the same effect as genetically ablating Apelin expression, synergizing with sunitinib to reduce tumor progression." (PMID 31267692, 2019). "We find that impairing Apelin expression from both, the epithelial tumor cells, as well as from cells in the tumor microenvironment, is key to reduce tumor growth." (PMID 31267692, 2019). "Implantation of apelin-overexpressing NSCLC cells into mice resulted in accelerated tumor growth in vivo with increased microvessel density (MVD)." (PMID 29875677, 2018). "Regulation of progression of tumor growth and metastasis is the most recently discovered function of apelin." (PMID 29875677, 2018).